TMEM259 (transmembrane protein 259)
Description:
May have a role in the ERAD pathway required for clearance of misfolded proteins in the endoplasmic reticulum (ER). Promotes survival of motor neurons, probably by protecting against ER stress.
Synonyms: C19orf6; MGC4022; ASBABP1; MBRL; MEMBRALIN; R32184_3
Tractability: Antibody: UniProt predicts a signal peptide or a membrane-spanning region. PROTAC: ubiquitination databases record sites on it; its protein half-life has been measured.
Gene: Protein-coding gene on chromosome 19 (1,009,648 to 1,021,179, reverse strand). Ensembl gene ENSG00000182087.
Subcellular location: Endoplasmic reticulum membrane
Subcellular location (Human Protein Atlas): Endoplasmic reticulum; Nuclear speckles
Gene Ontology:
Biological process: positive regulation of ERAD pathway; response to endoplasmic reticulum stress
Cellular component: endoplasmic reticulum membrane; endoplasmic reticulum
Genetic constraint (gnomAD): Loss-of-function variants: 25 observed, 36.01 expected, observed/expected ratio (o/e) 0.69, 90% interval 0.5 to 0.97. The synonymous counts are far from expectation, so gnomAD's model fits this gene poorly and the ratio says little. Missense variants: 890 observed, 735.29 expected, observed/expected ratio (o/e) 1.21, 90% interval 1.14 to 1.28. Synonymous variants: 476 observed, 331.93 expected, observed/expected ratio (o/e) 1.43, 90% interval 1.33 to 1.55.
Homologues: Orthologues: chimpanzee TMEM259 (99% identical), macaque TMEM259 (92% identical), pig TMEM259 (91% identical), dog TMEM259 (89% identical), guinea pig TMEM259 (83% identical), mouse Tmem259 (81% identical), rat Tmem259 (81% identical), tropical clawed frog tmem259 (66% identical), zebrafish tmem259 (66% identical), Drosophila melanogaster CG8405 (45% identical), Caenorhabditis elegans Y59C2A.2 (36% identical). Paralogues in human: NUF2 (9% identical).
Diseases named in the same sentence as TMEM259 in open-access papers:
TMEM259 is named in the same sentence as 5 diseases in open-access papers, as found by Europe PMC text mining. Sharing a sentence is not in itself a finding about the gene and the disease. The quoted sentences say what the papers report.
infection (1 paper, 2021). The state of being infected such as from the introduction of a foreign agent such as serum, vaccine, antigenic substance or organism. "A subset of genes was significantly translationally upregulated but showed no significant differential expression in the RNA-Seq analysis, reflecting differences of stringency between both methods (i.e., Parp14 and Dhx58) or specific changes in protein stability during infection (i.e., Tmem259)." (PMID 34346771, 2021).
TMEM259 also shares sentences with these, for which no sentence is quoted: amyotrophic lateral sclerosis (1 paper); gastric cancer (1); neurodegenerative disease (1); tumor (1).